CD4 (CD4 molecule)
Diseases named in the same sentence as CD4 in open-access papers (continued):
Sharing a sentence is not in itself a finding about the gene and the disease.
lymphopenia (continued). "All the same, in the peripheral blood, it has been already shown that treatment-induced lymphopenia is not a random process and susceptibility to intensive chemotherapy differs between T cells subsets (i.e., CD4, CD8, and Tregs)." (PMID 30069492, 2018). "The CD8+ count normalized rapidly but his CD4+ lymphopenia persisted until he was 5 months of age." (PMID 30038614, 2018). "A relative lymphopenia may reflect a lower number of CD4+ T helper lymphocytes, resulting in a poorer lymphocyte-mediated immune response to malignancies." (PMID 29089030, 2017). "It is a rare condition defined as a CD4+ T cell count persistently <300 cells/μl in the absence of known secondary causes of lymphopenia, such as HIV infection." (PMID 28493863, 2017). "Long-lasting severe CD4 lymphopenia may occur in CGD, likely due to both persistent immune activation and impaired T-cell production." (PMID 28553289, 2017). "Idiopathic CD4+ T cell lymphocytopenia is a rare condition characterized by persistently low CD4+ T cell count in the absence of known secondary causes of lymphopenia." (PMID 28493863, 2017). "Patients with visceral leishmaniasis and any form of immunodeficiency, such as idiopathic CD4+ T cell lymphocytopenia or immunosuppressive therapy, must be monitored closely for signs of relapse and may benefit from secondary prophylaxis." (PMID 28493863, 2017). "To determine whether the T‐cell lymphopenia in GIMAP1‐deficient mice also exhibits an age‐dependent profile, we enumerated CD4+ T cells in Gimap1f/fCD2Cre+ and control Gimap1f/f mice at 5 and 10 weeks of age." (PMID 27792288, 2017). "Active TB infection is known to cause CD4 and CD8 lymphopenia, and T-cell exhaustion and depletion." (PMID 29371544, 2017). "There are striking similarities in the clinical phenotype of patients with gain-of-function PI3K activity and patients with loss-of-function PTEN defects, such as immune dysregulation, lymphopenia, increased transitional B-cell counts, and reduced CD4/CD8 ratio." (PMID 27477328, 2017). "Importantly, however, the presence of the irrelevant CD4+ T cells prevents canonical lymphopenia-induced T-cell expansion of any transferred T cells." (PMID 27097762, 2016). "CD4/CD8 ratio is an indicator of CD4+ T cell lymphopenia and of CD8+ T cell activation and some comorbidities may depend on none of these factors." (PMID 27548257, 2016). "Nevertheless, only a part of the signs was explained by CD4 lymphocytopenia." (PMID 26491451, 2015). "Moreover, transfer of naïve CD4+CD45RBhigh CD4+ T cells in lymphopenic hosts such as Rag1/2−/− or SCID mice induces lymphopenia-induced T cell activation and colitis only in the absence regulatory T cells." (PMID 25944983, 2015). "Apoptosis may also play a role in the pathogenesis of some extraglandular manifestations of pSS and peripheral CD4+ lymphocytopenia." (PMID 26090503, 2015). "The spectrum of the disease has expanded to include Omenn syndrome, early onset autoimmunity, granuloma, chronic cytomegalovirus or EBV infection with expansion of gamma/delta T-cells, idiophatic CD4 lymphopenia and a phenotype resembling common variable immunodeficiency." (PMID 26186701, 2015). "We first enumerated blood T-cell subsets, finding the expected general lymphopenia in O mice on CR, which was not caused by T-cell (total CD4 or CD8) depletion." (PMID 25424641, 2015). "Thus, fast progressors (PB023 and PB028) displayed LNs T cell depletion of both Tfh and effector memory CD4 T cells consistent with global lymphopenia of memory cells observed in those animals." (PMID 26640894, 2015). "Nonetheless, Gimap5sph/sph mice exhibit a progressive reduction in circulating CD4+ T cells and the CD4+ T cells that remain after five weeks of age exhibit a lymphopenia-induced proliferation (LIP) phenotype (CD44high and CD62Llow), a T cell phenotype associated with autoimmunity." (PMID 25944983, 2015).
lymphopenia (continued). "Of the nine immunocompromised patients who relapsed, three were found to have a CD4 lymphopenia." (PMID 25831056, 2015). "Adipose inflammation may also be related to the spread of viral proteins, CD4+ T cell lymphopenia and/or microbial translocation, all of which are known to alter adipocyte homeostasis." (PMID 26402858, 2015). "The patients with CD4 lymphopenia were identified at the time of their VL diagnosis." (PMID 25831056, 2015). "On March 2008, the patient presented a complex clinical picture including an interstitial pneumonitis by Mycoplasma pneumoniae and Chlamydia pneumoniae, Epstein Barr and cytomegalovirus infections, tubulointerstitial nephritis, severe lymphopenia, and marked reduction of CD4 (214 cells/μL)." (PMID 26491451, 2015). "Our data demonstrates that pediatric sarcoma patients exhibit alterations in the distribution leukocytes whereby granulocyte cell counts are elevated in peripheral blood thus reducing the overall percentage of lymphocytes and CD4 lymphopenia that is more profound in ES patients." (PMID 26286851, 2015). "Thus, the lymphopenia observed in these animals resulted not only from CD4 T cell depletion but also CD8 T cells and B cells." (PMID 26640894, 2015). "During follow-up, this phenotype evolved into predominant CD4 lymphopenia." (PMID 25205547, 2014). "The patient had lymphopenia and low CD4+ counts (≤70 cells μl−1) during the follow-up." (PMID 28663813, 2014). "In parallel, Good’s syndrome is characterized by hypogammaglobulinemia and thymoma, low or absent B cells, variable defects in cell-mediated immunity with a CD4 T lymphopenia, an inverted CD4/CD8+ T-cell ratio and reduced T-cell mitogen proliferative responses." (PMID 24621280, 2014). "In this study, we investigated a consanguineous family with two affected siblings suffering from CID that evolved into predominant CD4 lymphopenia in order to define hitherto unknown genetic etiologies underlying this condition." (PMID 25205547, 2014). "Similarly when patient’s CD4 count decreases prevalence of leucopenia and lymphopenia increases (p < 0.05)." (PMID 24666771, 2014). "Be that as it may, in the hepatitis-inducing LCMV-WE infection that we have studied here, CD4+ T cell-lymphopenia seemed to induce an impaired intrahepatic CD8+ T-cell response and impaired intrahepatic virus control." (PMID 24466045, 2014). "Anemia, leucopenia, thrombocytopenia and lymphopenia were increased as CD4 count decreases." (PMID 24666771, 2014). "Recent data using anti-tumor models has demonstrated that strong stimulation via OX40 and OX40-L, 4-1BB activation or OX40 stimulation and lymphopenia could enhance CD4 CTL activity in a manner dependent on Eomesodermin." (PMID 24586481, 2014). "Routine laboratory tests showed low leukocyte count (3.5 × 103/ul), lymphopenia (16.6%), low platelets (132 × 103/ul), CD-4 T-cell count was lower than (15/ul), and positive serology for HIV and hepatitis C. Other routine investigations were normal including chest X-ray and ECG." (PMID 25174279, 2014). "Interestingly, CD4+ T/T-cell lymphopenia can be observed in the spleens of aged humans and aged Balb/c mice, when the function of the immune system is declining." (PMID 24586733, 2014). "Furthermore, HIV infection can directly result in lymphopenia as the infection progresses, leading to a decrease in CD4+ lymphocytes." (PMID 24666771, 2014). "In vivo TR2 deletion in CD4+ T cells combined with acute lymphopenia, however, does not lead to loss of tolerance." (PMID 24115907, 2013). "By use of the acute lymphopenia models of sublethal irradiation and anti-CD4 depleting antibody treatment, we focused on systems which were shown to drive T cell proliferation by increased availability of IL-7, a setting which amplifies signals from weak TCR/self-pMHC contacts." (PMID 24115907, 2013).
lymphopenia (continued). "In line with our findings on associations with clinical severity reported here, the lower prevalence of CD4 lymphocytopenia in our population could be related to more advanced disease in hospitalized subjects." (PMID 24358268, 2013). "Idiopathic CD4+ lymphocytopenia (ICL) is an immune deficiency characterized by persistently decreased CD4+ T lymphocyte numbers in the absence of HIV infection or other known causes of T cell depletion." (PMID 23383227, 2013). "Collectively, our findings suggest that CD4+ pre-RTEs have intrinsic advantages over “old” peripheral naïve T cells in the survival and lymphopenia-induced proliferation, enabling them to play an essential role in maintaining a diverse T cell repertoire in the periphery." (PMID 23409179, 2013). "The lymphopenia observed in rapamycin-treated mice was due to a decrease in CD4 and CD8 T cell populations, i.e. among CD3+T cells, the decrease in number was equally partitioned between CD4+ and CD8+ T cells, leading to a significant decrease in the overall T cell frequency." (PMID 24265670, 2013). "The BBDP rat strain is an extensively studied model of type 1 diabetes, occurring in association with profound T cell lymphopenia with severe reduction or absence of CD4 and CD8 T cells." (PMID 23890820, 2013). "CD8 + T cells and NK cells not only cause severe tissue injury, but also suppress proliferation of CD4+ Th1 cells and mediate apoptosis of CD4 + T cells, which could account for defective Th1 responses and lymphopenia in fatal ehrlichiosis." (PMID 22607204, 2012). "All patients with grade 3/4 CD4+ lymphopenia received prophylactic cotrimoxazol." (PMID 22396071, 2012). "Ongoing phase 3 trials should indicate whether IL-7 has a role in correcting lymphopenia in patients who fail to recover CD4 T cell counts under HAART (or in purging the viral reservoir )." (PMID 22958464, 2012). "As we have shown here that absolute lymphopenia correlates with lower CD-4 counts, an early identification of community-acquired pneumonia with lymphopenia, particularly with high LDH, should merit consideration for treatment with trimethoprim/sulfamethoxazole and steroids." (PMID 23882358, 2012). "It should be noted that the moderate decrease in Treg numbers in AAV patients was likely due to the global lymphopenia that is usually observed in these patients, especially during flares, whereas the frequency of Tregs within the CD4 compartment was similar to that of controls." (PMID 21494636, 2011). "Mouse studies have shown a functional link between lymphopenia and Treg instability, and suggest that the CD4+ T cell lymphopenia and reduced Treg numbers found in SLE patients may also be linked." (PMID 21708033, 2011). "Indeed M. genavense infection occurs in patients with profound CD4+ lymphopenia (50 cells/mm3 or less)." (PMID 22054169, 2011). "The significance of CD4 lymphopenia in our patients is uncertain." (PMID 20618932, 2010). "Notably, we found an unsuspected role for CD40L in the lymphopenia-induced proliferation of CD4+ T cells." (PMID 20856822, 2010). "To determine whether the blocking effect of MR1 on HNT CD4+ T cell proliferation was driven by lymphopenia and/or the HA antigen, we performed adoptive transfer experiments in lymphopenic MR1 treated BALB/c mice." (PMID 20856822, 2010). "Peripheral expansion of CD4+CD25hi Treg in vivo is regulated by both IL-2 and lymphopenia." (PMID 19270751, 2009). "• Early severe sepsis is characterized by CD4-lymphopenia and an increased presence of NK cells." (PMID 17129388, 2006). "CD4-lymphopenia as a consequence of apoptosis is a well-described finding in septic patients." (PMID 17129388, 2006). "Moreover, research indicates that toxic solutes originating in the gut bacterial flora could potentially hinder CD4+ T cell recovery on ART and contribute to the CD4+ T cell lymphopenia observed in INRs." (PMID 40801597, 2025).
lymphopenia (continued). "Furthermore, treatment with MEK inhibitors may promotes the recovery of CD4 T cells, a potentially valuable outcome in the management of immunosuppressive treatment-induced lymphopenia." (PMID 40894910, 2025). "Therefore, we examined whether the lymphopenia in the 17ZR101-infection led to impaired induction of peripheral antigen-specific CD4 effector T cell responses." (PMID 40096073, 2025). "Consistent with this notion, naïve CD4+ T lymphocytes can induce severe colitis dependently of commensal microbiota present in chronically lymphodeficient hosts, arguing that excess lymphopenia-induced proliferation of naïve cells can lead to immunopathology." (PMID 39630890, 2024). "In addition, the few cases of lymphopenia in chronic PCM could be related to the reduction in the CD4+ subpopulation in the blood and the high concentration of these cells in tissue granulomas." (PMID 38786672, 2024). "However, we acknowledged that the absence of detectable SARS-CoV-2-specific CD4 T cells in patients with severe lymphopenia may be attributed to the limited number of CD4 + T cells available for flow cytometry analysis." (PMID 38491050, 2024). "Furthermore, Ripk1ΔCD4Casp8 ΔCD4 and Ripk1ΔCD4Tnfr1−/− double-knockout mice rescued the peripheral T cell lymphopenia, revealing that RIPK1-deficient naive CD4+ and CD8+ cells and FoxP3+ regulatory T cells specifically die from TNF- and caspase-8-mediated apoptosis in vivo." (PMID 38734851, 2024). "Thus, CD4+ CD25+ T cells control the onset of autoimmunity in the context of lymphopenia-induced T cell proliferation; conditions found in immunocompromised, thymectomized, or young animals (< 3 weeks) in which the homeostasis of effector and regulatory T cells is still unbalanced." (PMID 38404584, 2024). "Notably, patients with lymphopenia demonstrated higher proportion of CD4+PD1+ T cells." (PMID 39266539, 2024). "Lymphopenia may explain the lower proportion of CD4+ T naive cells 4 days after sepsis onset." (PMID 39691721, 2024). "Moreover, lymphopenia in AD patients shows a tendency for preferential depletion of IFN-γ-producing T cells (both CD4+ and CD8+ T cells), which might result in Th2-deviated immune responses." (PMID 37373104, 2023). "Thus, CD4+ T lymphopenia, CD40 ligand absence, or interfered IFN-γ pathway could hamper macrophages to eliminate intracellular TM." (PMID 36180657, 2022). "However, low levels of T cell activation are associated to a better disease outcome; on the other hand, profound CD8+ T-cell lymphopenia, a high level of CD4+ and CD8+ T-cell activation and a high level of CD8+ T-cell senescence are associated with a higher mortality outcome." (PMID 35911748, 2022). "Furthermore, CD4+ lymphopenia was associated with non-response to chemotherapy, suggesting the important role of CD4+ T cells in controlling tumor progression." (PMID 35546670, 2022). "Nevertheless, in the cryptOsarc study, CD4 lymphocytopenia was not an independent risk factor for cryptococcosis consistent with our findings that in CINS patients with sarcoidosis had a higher CD4 T cell proportion and CD4/CD8 T cells ratio than non-sarcoidosis patients." (PMID 35425769, 2022). "With the results of lymphopenia in confection groups, the reduced NAb titers against both viruses correlate with decreased B and CD4+ T cell populations in peripheral blood, and thus the CD4+ T cell response could be more vital than CD8+ T cell response in protection against coinfection by NAb." (PMID 35107382, 2022). "In addition to HCV viremia, age-associated thymic insufficiency and/or impaired immune homeostasis by the damaged liver during cirrhosis may invariably lead to naïve CD4+ T cell lymphopenia and systemic immune activation." (PMID 35062255, 2021).
lymphopenia (continued). "Although a causal link between fingolimod-induced CD4+ T cell lymphopenia and cryptococcus infection has not been proven, decreased CD4+ T cell counts might be a risk factor for acute cryptococcal infection or a reactivation of a latent infection." (PMID 32036423, 2021). "Moreover, the sCD14 levels correlated with naïve CD4+ lymphopenia and effector/memory CD4+ and CD8+ T cell activation levels in our previous studies, potentially providing a linkage between microbial translocation and abnormal T cell level and T cell activation." (PMID 35062255, 2021). "In the present study, we found that the development of lymphopenia in severe patients was related to the significantly decreased absolute counts of CD4+ T cell and CD8+ T cell and reduced counts of CD19+B cell, indicating SARS-CoV-2 may impair cellular and humoral immunity at an early stage." (PMID 33390771, 2021). "In addition, there was an imbalance in the lymphocyte immune response in severe patients, who had more CD4 lymphopenia, more CD4-naïve cells and CD4 suppressor T cells, and fewer CD4 memory cells and regulatory T cells, compared to that in non-severe patients." (PMID 33539383, 2021). "Importantly, CD4+ T lymphopenia is correlated with postoperative MAEs in the present study." (PMID 34869652, 2021). "Marked lymphopenia was associated not only with the reduced CD3+ CD4+T-cell numbers, but also with the inhibition of their differentiation to effector memory cells from naive CD4+ T-cells, which play a particularly important role in the adaptive anti-infectious immunity." (PMID 32722596, 2020). "Hence, CD4+ T cell lymphopenia could be a reflection of CD4+ T cell redistribution throughout the body." (PMID 33384690, 2020). "Thus, we hypothesize that decreased thymic output of CD4+ T cells contributes to lymphopenia and compromised immune defense in sepsis." (PMID 32825352, 2020). "However, it remained unclear whether extrinsic mechanisms prevent LIP of lymphopenia-insensitive CD4+ T cells." (PMID 30792713, 2019). "The total numbers of CD4+ and especially CD8+ T cell populations in the lymph nodes (LNs) were significantly lower in Dicer-deficient animals in comparison to wild type littermate controls, thus demonstrating that T cell-specific deletion of Dicer leads to T cell lymphopenia in the periphery." (PMID 31130952, 2019). "In addition, a possibly underlying STK4 deficiency should be suspected and tested in patients with a clinical history of recurrent infections, CD4 lymphopenia and lymphoma and unknown genetic make-up." (PMID 30386345, 2018). "Prior TB and NTM infection were not statistically associated with CD4 or CD8 lymphopenia." (PMID 29371544, 2017). "The increase in % T lymphocytes in Vk#31 with high grade disease could represent a reciprocal change to the B lymphopenia occurring; however, the change in CD4:CD8 ratio with high-grade disease suggested a preferential expansion of CD8+ T cells and/or loss of CD4+ T cells." (PMID 27599546, 2016). "Thus, when patients exhibit marked CD4 lymphopenia and susceptibility to infections in the absence of a bleeding disorder, MST1 deficiency should be considered along with DOCK8 deficiency." (PMID 26801501, 2016). "However, the conversion of CD4+ T cells to an activated effector memory phenotype, with a high percentage of cells showing Ki-67 expression, occurred in both hNOJ (IR+) and hNOJ (IR−) mice, probably as a result of lymphopenia-induced homeostatic expansion." (PMID 23301078, 2013). "However, our data suggest that severe TB (as measured by the degree of wasting) can contribute to CD4 lymphocytopenia in co-infected subjects, and that it may be partly reversed by ATT." (PMID 24358268, 2013). "In BELFAST subjects, we had previously shown an association between the CD4 count and some nutritional markers, suggesting that potentially reversible nutritional and/or inflammation-related factors could be responsible for the CD4 lymphopenia in our aged group." (PMID 20507630, 2010).